MACROH2A2 (macroH2A.2 histone)
Description:
Variant histone H2A which replaces conventional H2A in a subset of nucleosomes where it represses transcription. Nucleosomes wrap and compact DNA into chromatin, limiting DNA accessibility to the cellular machineries which require DNA as a template. Histones thereby play a central role in transcription regulation, DNA repair, DNA replication and chromosomal stability. DNA accessibility is regulated via a complex set of post-translational modifications of histones, also called histone code, and nucleosome remodeling. May be involved in stable X chromosome inactivation.
Synonyms: H2AFY2
Tractability: PROTAC: UniProt records ubiquitination sites on it; ubiquitination databases record sites on it.
Gene: Protein-coding gene on chromosome 10 (70,052,544 to 70,112,282, forward strand). Ensembl gene ENSG00000099284.
Subcellular location: Nucleus; Chromosome
Subcellular location (Human Protein Atlas): Nucleoplasm
Gene Ontology:
Molecular function: chromatin DNA binding; protein binding; RNA polymerase II transcription regulatory region sequence-specific DNA binding; transcription cis-regulatory region binding; structural constituent of chromatin; DNA binding; protein heterodimerization activity
Biological process: brain development; dosage compensation by inactivation of X chromosome; establishment of protein localization to chromatin; negative regulation of gene expression, epigenetic; negative regulation of transcription by RNA polymerase II; negative regulation of transcription of nucleolar large rRNA by RNA polymerase I; positive regulation of keratinocyte differentiation; heterochromatin formation; nucleosome assembly
Cellular component: Barr body; chromatin; chromosome; chromosome, telomeric region; extracellular exosome; nucleoplasm; nucleus; nucleosome
Genetic constraint (gnomAD): Loss-of-function variants: 5 observed, 22.13 expected, observed/expected ratio (o/e) 0.23, 90% interval 0.12 to 0.47. The upper end of that interval is the gene's LOEUF score, 0.47, which puts it in group 2 of 6, group 1 being the genes least tolerant of losing a copy. Missense variants: 208 observed, 363.71 expected, observed/expected ratio (o/e) 0.57, 90% interval 0.51 to 0.64. Synonymous variants: 148 observed, 159.51 expected, observed/expected ratio (o/e) 0.93, 90% interval 0.81 to 1.06.
Homologues: Orthologues: chimpanzee MACROH2A2 (100% identical), macaque MACROH2A2 (99% identical), pig MACROH2A2 (99% identical), dog MACROH2A2 (99% identical), guinea pig MACROH2A2 (99% identical), rabbit MACROH2A2 (99% identical), mouse Macroh2a2 (98% identical), rat Macroh2a2 (98% identical), tropical clawed frog macroh2a2 (80% identical), zebrafish macroh2a2 (73% identical). Paralogues in human: MACROH2A1 (68% identical), H2AC18 (22% identical), H2AC19 (22% identical), H2AC20 (22% identical), H2AC21 (22% identical), H2AC1 (22% identical), H2AC25 (22% identical), H2AC6 (22% identical), H2AC11 (22% identical), H2AC12 (22% identical), H2AC13 (22% identical), H2AC14 (22% identical), and 15 more.
Diseases named in the same sentence as MACROH2A2 in open-access papers:
MACROH2A2 is named in the same sentence as 17 diseases in open-access papers, as found by Europe PMC text mining. Sharing a sentence is not in itself a finding about the gene and the disease. The quoted sentences say what the papers report.
glioblastoma (2 papers, 2023 to 2024). The most malignant astrocytic tumor (WHO grade IV). "Here, the authors identify histone variant macroH2A2 as a regulator of chromatin organisation resulting in the suppression of transcriptional programs of self-renewal in glioblastoma." (PMID 37244935, 2023). "In this work, we show that macroH2A2 is a negative regulator of self-renewal in glioblastoma stem cells, and repression of macroH2A2 abrogates cellular transitions from proneural to mesenchymal/astrocytic cellular states." (PMID 37244935, 2023). "ATAC-seq and macroH2A2 ChIP-seq results showed that macroH2A2 alters chromatin accessibility, regulates enhancer progenitor function, and represses the expression of tumor growth genes, thus antagonizing tumor self-renewal and inhibiting glioblastoma growth." (PMID 39199381, 2024).
melanoma (2 papers, 2023). A malignant, usually aggressive tumor composed of atypical, neoplastic melanocytes. "Loss or downregulation of macroH2A1 and macroH2A2 have been described in a number of malignancies, including bladder cancer, melanoma, lung cancer, and gastric cancer." (PMID 37244935, 2023). "MacroH2A1, present throughout normal skin, was retained in melanomas, whereas macroH2A2, detected primarily at low levels in the hair follicle in normal skin, was focally present in the tumour." (PMID 37605008, 2023). "For instance, macroH2A2 expression tends to be repressed in melanoma." (PMID 37244935, 2023). "It remains to be determined whether macroH2A2 antagonizes stemness programs in melanoma, as it does in GBM." (PMID 37244935, 2023). "Examining human melanoma-derived primary CAF cultures revealed homogenous levels of macroH2A1 protein, whereas macroH2A2 spanned almost an order of magnitude." (PMID 37605008, 2023).
breast carcinoma (1 paper, 2023). "In following, reactivation of macro-bound enhancers is associated with oncogenic programs in breast cancer and their repressive role is correlated with the activity of macroH2A2 as a negative regulator of BRD4 chromatin occupancy." (PMID 36823213, 2023).
glioma (1 paper, 2023). A benign or malignant brain and spinal cord tumor that arises from glial cells (astrocytes, oligodendrocytes, ependymal cells). "We found that low levels of MACROH2A2 transcription were associated with shorter overall survival in the high-grade glioma cohort collected by TCGA (log-rank p = 0.035) and in IDH-wildtype GBM patients in the Gravendeel cohort (log-rank p = 0.0085)." (PMID 37244935, 2023). "Collectively, our analyses of patient cohorts (bulk data) and single-cell transcriptomes generated from different groups consistently indicate that the transcription of MACROH2A2 is enriched in glioma cells with proneural or NPC-like states, and reduced at the infiltrating edge of the tumor." (PMID 37244935, 2023). "MACROH2A2 transcriptional levels did not stratify patients with IDH-mutant gliomas in the Gravendeel cohort or CIMP-positive tumors in the TCGA cohort." (PMID 37244935, 2023).
hepatoblastoma (1 paper, 2025). Hepatoblastoma (HB) is a malignant hepatic tumor and is the most common pediatric liver cancer. "Removal of MACROH2A2 from hepatoblastoma cells could alter the transcriptional ground state of cancer cells as well as their response to inflammatory cytokines, which is related to the interaction of cancer cells with immune cells in their microenvironment." (PMID 39816677, 2025).
tumor (7 papers, 2020 to 2025). "Accordingly, overexpression of macroH2A2 induced tumour cell dormancy and suppressed the growth of disseminated cancer cells into overt metastasis." (PMID 37605008, 2023). "Moreover, our investigation reveals a significant downregulation in the expression levels of these uEV-associated biomarkers after surgery, indicating the likely secretion of SRGN, FLI1, and MACROH2A2 by tumor cellular EVs." (PMID 39816677, 2025). "Variants of the macroH2A family, like macroH2A1 (coded by H2AFY gene) and macroH2A2 (coded by H2AFY2 gene) regulate gene expression important for differentiation, stem cell reprogramming and tumor suppression." (PMID 40655151, 2025).
cancer (5 papers, 2014 to 2025). A tumor composed of atypical neoplastic, often pleomorphic cells that invade other tissues. "MACROH2A2 encodes a replication-independent histone that represses transcription and restricts cellular plasticity in differentiated and cancer cells." (PMID 39816677, 2025). "MacroH2A1.1 and macroH2A2 inhibit proliferation and are associated with better cancer prognosis; while macroH2A1.2 is associated to cancer progression." (PMID 25003966, 2014). "Depletion of macroH2A2 significantly promoted the self-renewal properties in cancer cells, while overexpression antagonized self-renewal." (PMID 38542118, 2024). "Multiple investigations show the oncogenic roles of SRGN, FLI1, and MACROH2A2 in various cancers." (PMID 39816677, 2025). "The roles of SRGN, FLI1, and MACROH2A2 in carcinogenesis within other cancers are established, yet their mechanisms of action in uEVs of BC remain unclear." (PMID 39816677, 2025). "Last but not least, high expression of macroH2A2 can impede metastasis in Disseminated Cancer Cells (DCCs) by inhibiting cell cycle and oncogenic signaling programmes." (PMID 38542118, 2024).
MACROH2A2 also shares sentences with these, for which no sentence is quoted: colorectal cancer (2 papers); anal carcinoma (1); autism (1); ductal carcinoma in situ (1); Huntington disease (1); memory impairment (1); movement disorder (1); neurodevelopmental disorder (1); Parkinson disease (1); schizophrenia (1).